UBE2A (ubiquitin conjugating enzyme E2 A)
Description:
E2 ubiquitin-conjugating enzyme that accepts ubiquitin from the ubiquitin-activating enzyme E1 and transfers it to a E3 ubiquitin-protein ligase. In vitro catalyzes 'Lys-11', as well as 'Lys-48'-linked polyubiquitination. Together with the E3 enzyme BRE1 (RNF20 and/or RNF40), plays a role in transcription regulation by catalyzing the monoubiquitination of histone H2B at 'Lys-120' to form H2BK120ub1. H2BK120ub1 gives a specific tag for epigenetic transcriptional activation, elongation by RNA polymerase II, telomeric silencing, and is also a prerequisite for H3K4me and H3K79me formation. Involved in mitophagy by acting as a E2 ubiquitin-conjugating enzyme for PRKN. In association with the E3 enzyme UBR4, is involved in N-end rule-dependent protein degradation. In association with the E3 ubiquitin-protein ligase complex SIFI, inhibits the mitochondrial stress response by acting as a E2 ubiquitin-conjugating enzyme for UBR4 and KCMF1.
Synonyms: HR6A; hHR6A; RAD6A; UBC2; MRXS30; MRXSN
Tractability: Antibody: the Human Protein Atlas places it where antibodies can reach. PROTAC: ubiquitination databases record sites on it.
Gene: Protein-coding gene on chromosome X (119,474,802 to 119,591,083, forward strand). Ensembl gene ENSG00000077721.
Subcellular location: Late endosome; Lysosome
Subcellular location (Human Protein Atlas): Cytosol; Nucleoplasm; Plasma membrane; Flagellar centriole; Mid piece; Principal piece; Vesicles
Pathways (Reactome):
Metabolism of proteins: E3 ubiquitin ligases ubiquitinate target proteins; Synthesis of active ubiquitin: roles of E1 and E2 enzymes
Immune System: Antigen processing: Ubiquitination & Proteasome degradation
Gene Ontology:
Molecular function: protein binding; ubiquitin conjugating enzyme activity; ubiquitin protein ligase binding; ubiquitin-protein transferase activity; ubiquitin binding; ubiquitin-like protein transferase activity
Biological process: chromatin remodeling; DNA repair; G2/M transition of mitotic cell cycle; positive regulation of mitophagy; protein K11-linked ubiquitination; protein K48-linked ubiquitination; response to UV; DNA damage tolerance; proteasome-mediated ubiquitin-dependent protein catabolic process; protein polyubiquitination; ubiquitin-dependent protein catabolic process; protein ubiquitination
Cellular component: HULC complex; late endosome; lysosome; chromatin; cytosol; nucleoplasm
Gene-disease validity (ClinGen):
ClinGen rates the evidence that UBE2A causes each of these diseases.
syndromic X-linked intellectual disability Nascimento type (X-linked): Definitive.
Homologues: Orthologues: chimpanzee UBE2A (100% identical), dog UBE2A (100% identical), macaque UBE2A (100% identical), mouse Ube2a (100% identical), pig UBE2A (100% identical), rat Ube2a (100% identical), tropical clawed frog ube2a (100% identical), zebrafish ube2a (100% identical). Paralogues in human: UBE2B (95% identical), UBE2C (41% identical), UBE2N (41% identical), UBE2R2 (39% identical), UBE2I (39% identical), CDC34 (38% identical), UBE2NL (37% identical), UBE2W (35% identical), UBE2G2 (33% identical), UBE2T (33% identical), UBE2U (33% identical), UBE2Z (32% identical), and 12 more.
Diseases named in the same sentence as UBE2A in open-access papers:
UBE2A is named in the same sentence as 47 diseases in open-access papers, as found by Europe PMC text mining. Sharing a sentence is not in itself a finding about the gene and the disease. The quoted sentences say what the papers report.
Alzheimer disease (11 papers, 2016 to 2025). A progressive, neurodegenerative disease characterized by loss of function and death of nerve cells in several areas of the brain leading to loss of cognitive function such as memory and language. "Downregulation of UBE2A has been associated with brain amyloid plaque accumulation in Alzheimer’s disease patients." (PMID 41293127, 2025). "In the brains of Alzheimer’s disease patients, miRNA-7 deficiencies were found to be associated with a deficiency of the ubiquitin-conjugating enzyme UBE2A, which is necessary for amyloid degradation." (PMID 41245147, 2025). "Besides, Lukiw WJ, the author with the highest scientific productivity, published “Deficiency in the Ubiquitin Conjugating Enzyme UBE2A in Alzheimer’s disease (AD) is Linked to Deficits in a Natural Circular miRNA-7 Sponge (circRNA; ciRS-7),” which is widely cited." (PMID 36329875, 2022). "Additionally, CDR1as is implicated in Alzheimer’s disease by binding to miR-7, thereby reducing the ability of miR-7 to regulate ubiquitin-conjugating enzyme E2 A (UBE2A), a protein that decreases rapidly in Alzheimer’s disease (AD) and other neurological diseases." (PMID 33614648, 2021). "miR-7 directly targeting a-synuclein protein in Parkinson’s disease and ubiquitin protein ligaseA (UBE2A) in Alzheimer’s disease." (PMID 35652072, 2022). "Reduces the ability of miR-7 to thus upregulate UBE2A (a protein that rapidly decreases in Alzheimer's disease and other neurological diseases)." (PMID 32300345, 2020). "Alzheimer Disease is one of most dreadful neurological disorders associated with downregulation of number of miRNAs and there is a deficiency in the levels of Ubiquitin-Conjugating Enzyme (UBE2A) an enzyme essential for the proteolytic clearance of AD-amyloid peptides in human CNS." (PMID 32467674, 2020). "Additionally, CDR1as contributes to Alzheimer's disease by binding to miR-7, reducing the ability of miR-7 thus upregulate ubiquitin-conjugating enzyme E2 A (UBE2A), a protein that decreases rapidly in Alzheimer's disease and other neurological diseases." (PMID 32300345, 2020).
Intellectual disability (11 papers, 2013 to 2024). "For example, cognitive deficits have been observed in the presence of pathogenic variants in E2 and E3 encoding genes, as seen in Angelman syndrome (UBE3A) and intellectual disability (UBE2A, UBCl1, CUL4B, HUWE1, BRWD3)." (PMID 39596581, 2024). "In the same family 2, Ube2a, whose human ortholog is mutated in intellectual disability, contained a putative CREB1 BD outside a CpG island." (PMID 39596581, 2024). "In the present study, we used whole‐exome sequencing to identify a novel UBE2A splice site variant (c.241 + 1 G > A) in a Chinese proband with X‐linked intellectual disability." (PMID 35846913, 2022). "In conclusion, this report describes novel splice site variants (c.241 + 1 G > A) in the UBE2A gene resulting in an aberrant appearance and severe intellectual disability in a Chinese proband." (PMID 35846913, 2022). "Recently, UBE2A-Q93E was reported to be a novel pathogenic mutation associated with mild intellectual disability, and this mutation was proposed to disturb the catalytic microenvironment of UBE2A essential for its substrate lysine deprotonation." (PMID 36162503, 2022). "Moderate to severe intellectual disability and speech impairment have been reported in all patients with intragenic UBE2A mutations, including our patient." (PMID 31566921, 2019). "A novel splicing mutation (c.331‐2A>G) in UBE2A gene, inherited from his mother, was identified in a Chinese boy with intellectual disability and impaired speech." (PMID 31566921, 2019). "Herein, we present a Chinese boy with X‐linked intellectual disability carrying a novel acceptor splice site mutation in intron 5 (c.331‐2A>G) of the UBE2A gene (reference sequence: NM_003336.3)." (PMID 31566921, 2019). "In this study, we used exome sequencing to identify a novel UBE2A splice mutation, c.331‐2A>G, in a Chinese patient with intellectual disability." (PMID 31566921, 2019). "In addition, all probands with UBE2A deficiency syndrome have similar phenotypes, including characteristic facial appearance, speech anomalies, and intellectual disability." (PMID 35846913, 2022). "X‐linked intellectual disability type Nascimento (XIDTN), caused by mutations in ubiquitin‐conjugating enzyme E2A (UBE2A) gene, is characterized by moderate to severe intellectual disability, impaired speech, urogenital anomalies, skin abnormalities, and dysmorphic facial features." (PMID 31566921, 2019). "Therefore, mitochondrial dysfunction resulting from UBE2A mutations may lead to defects in synaptic transmission and intellectual disability in UBE2A deficiency syndrome." (PMID 31566921, 2019). "Identifying novel variants of UBE2A in XLID will help prevent disability and provide more opportunities to explore the molecular basis of intellectual disability." (PMID 35846913, 2022). "This suggests that the UBE2A/RAD18/PCNA axis might be at least partially responsible for the pathogenesis in mental retardation." (PMID 32344852, 2020). "However, a potential role of UBE2A-mediated monoubiquitination of H2B in mental retardation is still to be elucidated." (PMID 32344852, 2020). "Unlike previous reports, our milder patient with UBE2A splice mutation presented with intellectual disability, speech impairment, and white matter abnormalities, without skin anomalies, urogenital abnormalities, seizures, and dysmorphic facial features." (PMID 31566921, 2019).
breast carcinoma (5 papers, 2019 to 2024). "According to the risk heatmap, RBBP8 was downregulated in the high-risk group, indicating its tumor suppression potential in breast cancer, and UBE2A acted as a tumor-accelerating gene because it was upregulated in the high-risk group." (PMID 36713553, 2022). "The hazard ratio of other six genes (FAAP20, RRM2B, UBE2A,RAD50,MRE11, and RPA3) was >1, regarded as risk factors in developing breast cancer." (PMID 36713553, 2022). "In progesterone receptor-negative breast cancer patients, the expression level of UBE2V2 and UBE2A was higher than in patients with progesterone receptor-positive breast cancer." (PMID 36713553, 2022). "A series of twelve cancer driver gene expressions were identified to be associated with transcription factors, of which CCR7, BRD7, DDX3X, and UBE2A were upregulated in breast cancer tissues, and the others were downregulated in breast cancer tissues." (PMID 34507558, 2021). "In total, 11 DNA repair genes (UBE2A, RBBP8,RAD50, FAAP20, RPA3, ENDOV, DDB2, UBE2V2,MRE11, RRM2B, andPARP3) were preserved as prognostic genes to estimate risk score, which was applied to establish the prognostic model and stratified breast cancer patients into two groups with high or low risk." (PMID 36713553, 2022). "A total of 11 DNA repair genes, namely, UBE2A, RBBP8,RAD50, FAAP20, RPA3, ENDOV, DDB2, UBE2V2,MRE11, RRM2B, andPARP3, were involved in the prognostic model for breast cancer patients." (PMID 36713553, 2022). "We also identified and validated the RASEs of several genes in DNA damage/repair pathways, and identified their functions or dysregulated expression pattern with breast cancer, including PARK758, UBE2A and UBE2D359, NPM160, ERCC161, CSNK1E62, CENPX63, and SWI564." (PMID 38926398, 2024). "The expression level of DDB2, RPA3,RAD50, RRM2B, and UBE2A was higher in breast cancer tissues with lymph node metastasis compared with breast cancer tissues without lymph node metastasis, which was estimated by the distribution of their expression level between N0 and N1–N3 stages." (PMID 36713553, 2022).
melanoma (2 papers, 2019 to 2021). A malignant, usually aggressive tumor composed of atypical, neoplastic melanocytes. "As Rad6 is encoded by two genes, namely, UBE2A (RAD6A) and UBE2B (RAD6B), in humans, we compared their expressions in melanomas and normal melanocytes." (PMID 31683936, 2019).
multiple myeloma (2 papers, 2022 to 2024). "In addition, an RNA-seq signature involving UBE2A can predict the prognosis of multiple myeloma (MM)." (PMID 35210429, 2022). "A predictive model developed by Mohamad and others, based on five genes including CKS1B, CCT2, PRKDC, NONO, and UBE2A, successfully predicted the prognosis of patients with multiple myeloma and has been validated in several independent datasets." (PMID 39046884, 2024).
X-linked intellectual disability (2 papers, 2024). An X-linked intellectual deficiency in which not enough information is known, reported or published to indicate whether a gene causes non-syndromic or syndromic presentations. "Ube2b, a member of family 2, is required for neurite growth and is the paralog of Ube2a, the murine orthologue of UBE2A mutated in X-linked intellectual disability." (PMID 39596581, 2024). "Several X-linked intellectual disability (XLID) patient mutations within UBE2A cluster at this interface 52,54,55." (PMID 38182926, 2024).
X-linked intellectual disability type Nascimento (2 papers, 2013 to 2022). "Haploinsufficiency of UBE2A underlies the X-linked intellectual disability type Nascimento (XIDTN, OMIM #300860), also known as UBE2A deficiency syndrome." (PMID 35935361, 2022).
cervical cancer (1 paper, 2019). A primary or metastatic malignant neoplasm involving the cervix. "UBE2A is generally overexpressed in cervical cancer and is responsible for malignant transformation and chromosomal instability." (PMID 31766427, 2019).
Cognitive impairment (1 paper, 2022). Abnormal cognition is characterized by deficits in thinking, reasoning, or remembering. "Current studies mainly focus on cognitive impairment and skeletal muscle metabolism, but we have not found reports that UBE2A is directly related to sepsis." (PMID 35345523, 2022).
diabetes (1 paper, 2022). "UBE2A may be associated with increased skeletal muscle protein catabolic activity in a number of diseases and malnutrition states, such as cancer, sepsis, and diabetes." (PMID 35345523, 2022).
glioma (1 paper, 2022). A benign or malignant brain and spinal cord tumor that arises from glial cells (astrocytes, oligodendrocytes, ependymal cells). "The mass spectrometry data showed that HDACi causes the downregulation of RAD18 and UBE2A, an E3 ubiquitin ligase and an E2 ubiquitin-conjugating enzyme respectively, in TMZ-exposed glioma cells." (PMID 35365623, 2022).
hypospadias (1 paper, 2020). Hypospadias is the displacement of the urethral meatus on the ventrum of the penis. "And the deletion encompassing SLC25A43, LOC100303728, SLC25A5, CXorf56, UBE2A, NKRF, and SEPT6, is associated with hypospadias." (PMID 32515122, 2020).
Insulin resistance (1 paper, 2025). Increased resistance towards insulin, that is, diminished effectiveness of insulin in reducing blood glucose levels. "In addition, the ubiquitin-conjugating enzyme UB2O, related to UBE2A, promotes insulin resistance and obesity in MetS animal models." (PMID 41293127, 2025).
muscular atrophy (1 paper, 2024). The loss of muscle tissue due to inactivity or disease. "The role of UBR4 E3 activity in promoting various diseases such as cancer and muscular atrophy would imply that modulation of UBR4 hemiRING E3 activity might have therapeutic value (for example, by disruption of the UBE2A–hemiRING interface)." (PMID 38182926, 2024).
ovarian carcinoma (1 paper, 2022). A malignant neoplasm originating from the surface ovarian epithelium. "It has been reported that increased UBE2A expression predicts poor survival in patients with ovarian cancer." (PMID 35210429, 2022).
psychosis (1 paper, 2019). "Furthermore, in MDD patients with psychosis, the mRNA level of UBE2A and KAT2A was increased (by 53 and 43%, respectively; p < 0.05) compared to controls." (PMID 30377985, 2019).
Sepsis (1 paper, 2022). Sepsis is defined as life-threatening organ dysfunction caused by a dysregulated host response to infection. "CLIC1, UFD1, SEPT9, and UBE2A are new biomarkers found by us through the random forest model, and there is no research report related to sepsis so far." (PMID 35345523, 2022).
cancer (8 papers, 2019 to 2024). A tumor composed of atypical neoplastic, often pleomorphic cells that invade other tissues. "Crucially, expression of UBE2A mutants reduced the expression levels of most cancer stem cell marker genes including those of LGR5 and ID1 and increased those of KRT20 and MUCs." (PMID 38182897, 2024). "Biological variables associated to a high risk of progression included CIP2A levels, the expression levels of the polycomb group BMI1 gene, the activation of beta-catenin, specific gene signatures, and mutations in cancer-associated genes such as ASXL1, IKZF1, RUNX1, SETD1B, GATA2, MLL, and UBE2A." (PMID 31709190, 2019). "Survival analysis examining high expression levels of three of these genes (UBE2A, MAGEA2 and UTP14A) corresponded with poorer survival in five different cancers." (PMID 31772231, 2019).
tumor (8 papers, 2015 to 2026). "NDRG1 contributes to tumor aggressiveness by cell proliferation and lipid metabolism regulation, whereas GAPVD1, INPP5A, TCN1, SAV1, RBBP8, SPIB, and UBE2A also exhibit oncogenic or tumor-suppressive properties associated with prognosis." (PMID 41511940, 2026). "Collectively, hsa_circ_0001394 and UBE2A serve as tumor promotors while miR-527 acts as a suppressor in HCC progression." (PMID 35210429, 2022). "We discovered that protein modification-related, including HDGF, SIRT-7, UBE2A, and UCHL5, elevated expression in tumor tissues." (PMID 40041484, 2025).
infection (3 papers, 2015 to 2023). The state of being infected such as from the introduction of a foreign agent such as serum, vaccine, antigenic substance or organism. "Teasing apart how DENV, or other host response to infection, mediates this change in UBE2A and DDB1 expression would be interesting." (PMID 26566123, 2015).
UBE2A also shares sentences with these, for which no sentence is quoted: neurological diseases (4 papers); hepatocellular carcinoma (2); metastatic melanoma (2); onychodystrophy (2); X-linked Nascimento-type intellectual disability syndrome (2); acute lymphoblastic leukemia (1); adenocarcinoma (1); chronic myeloid leukemia (1); ciliopathy (1); Esophageal carcinoma (1); genetic disorders (1); Hirsutism (1); Infertility (1); leukemia (1); lung carcinoma (1); lymph node metastasis (1); malnutrition (1); Micropenis (1); neurodegenerative disease (1); neurodevelopmental disorder (1); Obesity (1); oligospermia (1); Parkinson disease (1); psychiatric diseases (1); rhabdomyosarcoma (1); squamous cell carcinoma (1); X-linked syndromic mental retardation (1).